CCAT2 (colon cancer associated transcript 2)
Diseases named in the same sentence as CCAT2 in open-access papers (continued):
Sharing a sentence is not in itself a finding about the gene and the disease.
cancer (continued). "Colon cancer associated transcript 2 (CCAT2), higher expressed in cancer tissues than that in adjacent mucosa, can also be a diagnostic and prognostic biomarker of CRC." (PMID 27966450, 2017). "Ccat2 (colon cancer-associated transcript 2) is an important transcript that was proven to have regulatory effects in several cancer types." (PMID 29206174, 2017). "Long non-coding RNA colon cancer-associated transcript 2 (CCAT2) is commonly investigated in a number of cancers." (PMID 27833083, 2016). "A growing body of studies have indicated the underlying molecular mechanisms of CCAT2 in cancer origination and development by regulating the Wnt/β-catenin signaling pathway." (PMID 27833083, 2016). "Meanwhile, the mechanistic investigation revealed that the lncRNA CCAT2 regulates cancer metabolism in vitro and in vivo in an allele-specific manner by binding the Cleavage Factor I (CFIm) complex with distinct affinities for the two subunits (CFIm25 and CFIm68)." (PMID 38243936, 2024). "Those with elevated CCAT2 levels face a higher risk of cancer-related mortality, indicating that CCAT2 could serve as both a predictive biomarker and a therapeutic target for EC." (PMID 39857631, 2024). "LncRNA CCAT2 (Colon Cancer Associated Transcript 2), which is located at the 8q24 amplicon of cancer risk-associated rs6983267 SNP was reported to promote the glycolysis as well as glutamine metabolism in a variety of cancers." (PMID 33849550, 2021). "Additionally, novel insight regarding CCAT2’s implication in promoting cancer-associated genomic instability hints towards the multiple implications of these transcripts across the various types of cancers associated with chromosomal abnormalities." (PMID 34830370, 2021). "Moreover EVs are becoming increasingly important in monitoring cancer progression and therapy, since they are able to carry specific disease biomarkers such as Glypican-1, colon cancer-associated transcript 2, CD63, CD24, and many others." (PMID 31281356, 2019). "Interestingly, CCAT2 has been shown to be implicated in cancer metabolism by influencing the glutaminase splicing." (PMID 31416190, 2019). "Therefore, we performed this meta-analysis to investigate the association between CCAT2 level and metastasis & prognosis in malignant tumors." (PMID 29088900, 2017). "Moreover, in different populations, CCAT2 gene polymorphisms have been linked to the risk or therapeutic response for numerous cancer types, including colon, kidney, thyroid, larynx, lung, and myeloid cancer in different populations." (PMID 31398859, 2019). "Thus, both CCAT1 and CCAT2 have been associated with increased risk of cancer and have been shown to regulate multiple molecular pathways to promote cell proliferation, metastasis, and cancer metabolism." (PMID 28793797, 2018). "However, little is known regarding how this altered splicing affects other cellular processes, or whether the differing alleles of CCAT2 target the splicing complex to different chromatin locations to affect cancer development." (PMID 29113413, 2017). "BC that tested positive for the ERα subtype had low levels of CCAT2 expression despite reports that CCAT2 promotes carcinogenesis in several cancers." (PMID 41459628, 2026). "This investigation has identified a dual role of CCAT2 in controlling both tumorigenesis and the stemness of cancer cells in luminal cancer of the breast." (PMID 41459628, 2026). "Studies have found that by overexpressing or knocking down CCAT2, reducing CCAT2 can increase miR-145, thereby inhibiting the proliferation of cancer cells." (PMID 39026978, 2024). "Therefore, we propose CCAT1 and CCAT2 as novel biomarkers to identify patients at higher risk of recurrence who may profit from intensified imaging-based follow-up regimens to timely detect cancer recurrence and initiate therapy." (PMID 37347737, 2023).
cancer (continued). "Functionally, CCAT2 is considered to be a therapeutic target because its depletion can block cancer cell proliferation and invasiveness." (PMID 35170195, 2022). "CCAT2 is upregulated in multiple types of cancer and plays an oncogenic role in cell proliferation, invasion, and metastasis." (PMID 35538075, 2022). "Therefore, CCAT2 could be considered a valuable pan-cancer biomarker that is associated with a more aggressive disease course, one with potential as a therapeutic target of new treatments or for use in strategies for overcoming chemoresistance and radioresistance." (PMID 34830370, 2021). "The role of CCAT2 in either initiating or promoting the oncological phenotype of multiple cancer types is still an expanding niche in the area of tumor-associated non-coding RNAs." (PMID 34830370, 2021). "Recent studies have also highlighted CCAT2 as having multiple miRNA regulatory targets, acting as one of the main pro-neoplastic drivers in various human cancers." (PMID 34830370, 2021). "The regulatory roles of CCAT2 in cancer therapeutic resistance are related to its direct inhibition of tumor suppressor miRNAs and through its effect on the DNA damage response pathway and chromosomal instability." (PMID 34830370, 2021). "Although more in-depth studies on the intricate regulatory functions of CCAT2 in cancer are needed, it has the potential to be used as a prognostic biomarker and as a possible therapeutic target in CRC." (PMID 34830370, 2021). "The lncRNA colon cancer-associated transcript 2 (CCAT2), which is overexpressed in CRC tissues, can promote cancer cell proliferation." (PMID 34778084, 2021). "The study revealed that CCAT2 was substantially overexpressed in cancer tissues compared to paired normal tissues, and this increase in CCAT2 levels correlated with a greater tumor volume, higher TNM grades, advanced clinical stage and a poor OS in patients." (PMID 34527584, 2021). "CCAT2 expression levels and their influence on cancer progression have been assessed in various cancer types and compared with survival data and prognostic factors, including proliferation, tumor size, migration, and metastasis." (PMID 34830370, 2021). "For example, lncRNABORG facilitates the survival and chemoresistance of TNBC, while lncRNA CCAT2 promotes TNBC oncogenesis by regulating the stemness of cancer cells." (PMID 33088216, 2020). "Our results demonstrate that in PC-3 cells the cancer-associated lncRNAs CCAT1 and CCAT2 are specifically m6A methylated." (PMID 32218194, 2020). "Surprisingly, large-scale studies have revealed that several lincRNAs are transcribed from the chr8q24 locus, such as CCAT1, CCAT2, PVT1, PCAT1, and PRNCR1; all of these encompass multiple cancer-associated variants." (PMID 32523949, 2020). "Overexpression of CCAT2 has been found in a wide range of cancers, in which it promotes the proliferation, invasion, migration, and survival of cancer cells." (PMID 32249459, 2020). "Although several studies have revealed that lncRNAs on 8q24, including PRNCR1, CCAT2 and PCAT1, encompass the cancer predisposition SNPs, the prognostic significance of these lncRNAs in GC patients has not yet been fully explored." (PMID 32117633, 2020). "As previously reported, lncRNA CCAT2 promotes cancer progression by increasing MYC gene expression in cancer cells." (PMID 32230936, 2020). "In the last years, another lncRNA, the colon cancer-associated transcript 2 (CCAT2), attracted the attention of researchers because of its dysregulation in cancer." (PMID 30884898, 2019). "CCAT2 is overexpressed in many cancer tissues, and it participates in tumor cell proliferation, invasion, and motility." (PMID 31275444, 2019). "Among long non-coding RNAs (lncRNAs) located in the chromosome 8q24 loci and involved in the carcinogenesis are colon cancer associated transcript 2 (CCAT2) and cancer susceptibility candidate 8 (CASC8)." (PMID 31398859, 2019).
cancer (continued). "For example, colon cancer associated transcript 2 (CCAT2) is upregulated in CRC and can promote cancer cell migration and metastasis." (PMID 31685807, 2019). "Further studies confirmed the involvement of CCAT2 in the tumorigenesis of many other cancers, including cervical cancer, bladder cancer, ovarian cancer, hepatocellular carcinoma, glioma, gastric cancer and breast cancer." (PMID 29298720, 2018). "Starkly increased CCAT2 gene expression levels were found in 12/48 (25%) of cancer tissue samples compared with their corresponding ANCTs." (PMID 28480695, 2017). "Starkly increased CCAT2 gene expression levels were observed in 12/48 (25%) of cancer tissue samples, as compared with their corresponding ANCTs." (PMID 28480695, 2017). "Recent studies have extensively investigated the regulatory roles of CCAT2 in several types of cancer origination and progression." (PMID 27833083, 2016). "The lncRNA CCAT2 is an imprinted and maternally expressed gene, which promotes the progression of lung and gastric cancers." (PMID 27283598, 2016). "Compared with para-cancer tissues, the CCAT2 expression was significantly upregulated in 28 cancer tissues (P<0.05)." (PMID 27015551, 2016). "Furthermore, via its interaction with EZH2, CCAT2 inhibits the production of p15 in cancer of the breast cells." (PMID 41459628, 2026). "Previous studies have verified that miR-145 could be regulated by lncRNA CCAT2 and lncRNA PVT1, which are associated with the malignant phenotype of several cancers." (PMID 38243936, 2024). "Furthermore, insights into other cancer types are provided through examples like tamoxifen-resistant MCF7 cells in which CCAT2 modulates the hsa-miR-145-5p/AKT3/mTOR axis, controlling cell behavior." (PMID 37760852, 2023). "In addition, previous studies exhibited that CCAT2 activates cancer progression and metastasis through the TGF-β1 signaling pathway." (PMID 36482069, 2022). "Moreover, upregulation of CCAT2 promoted tumorigenesis process via alterations in several cancer‐related pathways including Wnt and MAPK pathways." (PMID 34409736, 2021). "CCAT2 acts as sponge for some tumour suppressor miRNAs, thus promoting cancer evolution." (PMID 34409736, 2021). "The knockdown of CCAT2 suppressed cell proliferation and promoted apoptosis in cancer cells." (PMID 34204094, 2021). "CCAT2 regulates the metabolism of cancer cells by binding to the cleavage factor I (CFIm) complex." (PMID 34499007, 2021). "explored the expression of CCAT2 in 33 cancer types and 13,285 tumor patients." (PMID 34527584, 2021). "Calcitriol stimulation highlighted an inhibitory effect on CCAT2’s regulatory activity by decreasing the affinity between the transcription factor TCF7L2 and the MYC promoter, hindering its expression and therefore supporting a possible place for calcitriol as an inhibitor of CCAT2 in cancer." (PMID 34830370, 2021). "It has been reported that CCAT2 functions as an oncogene in multi-type cancers." (PMID 34499007, 2021). "Therefore, the implications of CCAT2 in different cancer types, emphasizing all the influential cancer-specific mechanisms and highlighting its potential biomarker and therapeutic use, are within the scope of this review." (PMID 34830370, 2021). "Moreover, downstream of the Wnt/β-catenin pathway, the Wnt-induced-secreted-protein-1 (WISP1) was also significantly upregulated in CCAT2 active cancers." (PMID 34830370, 2021). "CCAT2 inhibited miR‐145 maturation and increased metastatic potential of cancer cells." (PMID 34409736, 2021). "For instance, lncRNA GAS5 and CCAT2 have been indicated as sponges in promoting cancer development." (PMID 33393590, 2021). "Increasing evidence has verified the potential of CCAT2 in human cancers." (PMID 34499007, 2021). "Meanwhile, CCAT2 expression is the highest in stage II of human cancer, followed by stage III." (PMID 32908615, 2020). "Recently, an increasing number of studies have shown that CCAT2 might play important roles in cancer progression." (PMID 33371204, 2020).
cancer (continued). "As CCAT2 has been shown to promote cancer growth and metastasis in several types of cancers, our findings that vitamin D inhibits CCAT2 shed light on a novel mechanism of how vitamin D can prevent cancer metastasis." (PMID 32230936, 2020). "Besides ANRIL, CCAT2, PCAT1, HULC, and CUPID1/2, there are numerous other cancer-associated lncRNAs listed in the relevant databases, several of which contain disease-associated SNPs." (PMID 33329688, 2020). "Finally, 111 validated target gene symbols were identified, and GO and KEGG demonstrated that the CCAT2 validation target was significantly enriched in several pathways, including microRNAs in the cancer pathway." (PMID 32908615, 2020). "CCAT2 is overexpressed in various types of cancers and may contribute to tumor growth, metastasis, and chromosomal instability by increasing MYC expression." (PMID 32523949, 2020). "Besides, breast cancer antiestrogen resistance 4 (BCAR4), lncRNA-ROR (ROR, regulator of reprogramming), colon cancer associated transcript 2 (CCAT2), DSCAM-AS1, and LINC00894 are also reported to enhance or attenuate tamoxifen resistance." (PMID 32420379, 2020). "Increased expression of CCAT2 has been found in a wide range of cancers, promoting tumor growth, cell cycle progression, migration, invasion, metastasis, and inhibiting apoptosis, however, the function of CCAT2 in PDAC was still unknown." (PMID 29298720, 2018). "As emerging stars in cancer biomarkers, more and more lncRNAs were identified, and some functioned as oncogenes, such as CCAT2, HOTTIP and TUG1, while some may be acted as tumor suppressor genes, such as MEG3, GAS5, ANRIL." (PMID 28977885, 2017). "Therefore, we performed this meta-analysis to investigate the lymph node metastasis, distant metastasis and clinical prognostic role of overexpression CCAT2 in human cancers." (PMID 29088900, 2017). "In conclusion,CCAT2 might be served as a novel molecular marker for predicting metastasis and prognosis in various human-cancers." (PMID 29088900, 2017). "According to these results, we found that overexpression of CCAT2 could predict poor OS in various cancers." (PMID 29088900, 2017). "Furthermore,by combining HRs from the Cox multivariate analyses, we observed that CCAT2 was an independent prognostic factor of OS for cancer patients (pooled HR 2.23 [95 % CI 1.68–2.96,P<0.00001])." (PMID 29088900, 2017). "Specifically, the paradoxically higher CCAT2 levels in AP than CRC in our study probably suggest that AP may need high level of carcinogenic factors like CCAT2 to convert to carcinoma." (PMID 29176650, 2017). "Moreover, microsatellite-stable (MSS) cancers have higher CCAT2 expression than microsatellite-unstable (MSI-H) tumors and the adjacent normal colon mucosa." (PMID 26637808, 2016). "The biological function of CCAT2 as an oncogene in various human cancers suggested that it might be a potential and improved biomarker in the therapeutic of patients." (PMID 27833083, 2016). "To investigate this hypothesis, we evaluated the expression of CCAT2 in non-cancer and BC tissues and, in a large independent set of primary tumors the related expression with clinical, histological, pathological and other biological factors." (PMID 24077681, 2013). "Thus, CCAT2 plays a pivotal role in the tumor–stroma immune interplay within the tumor microenvironment, holding potential as a diagnostic and prognostic biomarker for CRC treatment while also offering insights into other cancer contexts." (PMID 37760852, 2023). "CCAT2 (Colon cancer associated transcript 2) is known to enhance Wnt/β-catenin signaling activity by binding to TCF and increasing its transcriptional activity subsequently activating the cascade of downstream gene expression crucial for cancer progression and invasion." (PMID 34552611, 2021).
cancer (continued). "Furthermore, the upregulation of the lncRNAs long stress-induced non-coding transcript 5 (LSINCT5), colon cancer-associated transcript 2 (CCAT2), competing endogenous lncRNA 2 (CERNA2), PVT1, and urothelial cancer-associated 1 (UCA1) have also been implicated in cancer-promoting mechanisms of OC." (PMID 34404407, 2021). "Besides, the regulation mechanism of CCAT2 in human cancer is still unclear." (PMID 32908615, 2020). "Additionally, the lncRNA colon cancer-associated transcript 2 (CCAT2) enhances WNT activity by binding to TCF7L2, a pivotal transcription factor in the WNT signalling pathway, and facilitates MYC activity, thereby enhancing cancer cell invasion and metastasis." (PMID 29137343, 2017). "The lncRNA CCAT2 (colon cancer-associated transcript 2) transcript maps to the highly conserved 8q24.21 region encompassing rs6983267; CCAT2 plays a crucial role in promoting tumor metastasis, growth, and chromosomal instability in colon, lung, breast, and gastric cancers." (PMID 27283598, 2016). "Moreover, CCAT2 was shown to promote cancer growth, metastasis, and induce chromosomal instability, and CCAT2 upregulated MYC expression through the activation of the Wnt signaling pathway by promoting TCF7L2 transcriptional activity rather than by increasing the quantity of TCF7L2." (PMID 26307974, 2015). "On the other hand, the nuclear accumulation of CCAT2 interacts with a pseudogene of OCT4 called OCT4‐PG1, which encourages the development of cancer stem cells." (PMID 41459628, 2026). "In contrast, nuclear overexpression of CCAT2 led to upregulation of OCT4-PG1 and the induction of cancer cell stemness." (PMID 36672487, 2023). "Professor Chen confirmed that, in colon cells, lncRNA CCAT2 induces chromosome instability through BOP1-AURKB signals, thus promoting the occurrence of cancer." (PMID 35237659, 2022). "Also, in the 8q24 region, lncRNAs prostate cancer-associated transcript 1 (PCAT1) and colon cancer-associated transcript 2 (CCAT2) by affecting DNA break repair and chromosome instability play a role in cancer development, and polymorphisms in these lncRNAs were crucial risks of cancers." (PMID 34337048, 2021). "This interplay between CCAT2, MYC, and WNT molecules has been explored and confirmed in multiple cancers in recent years and is responsible for the main pro-tumorigenic roles of CCAT2." (PMID 34830370, 2021). "However, the clinical value of CCAT2 in cancers remains unclear." (PMID 29088900, 2017). "The lncRNAs such as MALAT1, GAS5, ANRIL, PVT1, CCAT2 and HOTAIR etc. were found to be novel promising biomarkers to predict a poor prognosis in human cancers." (PMID 28594897, 2017). "However, overexpression of CCAT2 in MCF-7 cells through pMX retroviral nuclear expression vector accumulated CCAT2 in the nucleus, leading to upregulation of OCT4-PG1, a pseudogene of stem gene OCT4, thereby promoting the cancer cell stemness." (PMID 36672487, 2023). "In addition to bolstering cancer cell proliferation, migration, and invasion in the context of CRC, CCAT2′s upregulation in CRC tissues enhances cell growth and metastasis by interacting with TAF15 to stimulate RAB14 transcription." (PMID 37760852, 2023). "CCAT2 was reported to induce chromosomal instability and metastases and modulate MYC expression, known to regulate kinds of axis controlling molecular process and cancer metabolism." (PMID 35170195, 2022). "On the other hand, CCAT2 interacts with the RNA binding protein (RBP) ELAVL1/HuR at the nuclear level, a key factor involved in mRNA stabilization, previously shown to promote proliferation, apoptosis, and differentiation in multiple types of cancer." (PMID 34830370, 2021). "Other malignant tumors are no exception, LncRNA CCAT2 and UCA1 can activate Wnt and promote the development, migration and invasion of BC." (PMID 34135756, 2021).